TNFRSF17 (TNF receptor superfamily member 17)
Description:
Receptor for TNFSF13B/BLyS/BAFF and TNFSF13/APRIL. Promotes B-cell survival and plays a role in the regulation of humoral immunity. Activates NF-kappa-B and JNK.
Synonyms: CD269; BCM; BCMA; TNFRSF13A
Tractability: Antibody: an approved drug acts on it; its Gene Ontology location is reachable by antibodies, with high confidence; UniProt places it where antibodies can reach, with medium confidence; UniProt predicts a signal peptide or a membrane-spanning region. PROTAC: ubiquitination databases record sites on it. Other modalities: an approved drug acts on it.
Target class: Membrane receptor
Gene: Protein-coding gene on chromosome 16 (11,965,210 to 11,968,068, forward strand). Ensembl gene ENSG00000048462.
Subcellular location: Cell membrane; Endomembrane system
Subcellular location (Human Protein Atlas): Golgi apparatus; Mitotic spindle
Pathways (Reactome):
Immune System: TNFs bind their physiological receptors
Gene Ontology:
Molecular function: protein binding; signaling receptor activity
Biological process: signal transduction; tumor necrosis factor-mediated signaling pathway
Cellular component: membrane; plasma membrane; endomembrane system
Genetic constraint (gnomAD): Loss-of-function variants: 10 observed, 9.98 expected, observed/expected ratio (o/e) 1, 90% interval 0.62 to 1.66. That is too few expected variants to judge how well the gene tolerates losing a copy. Missense variants: 301 observed, 235.12 expected, observed/expected ratio (o/e) 1.28, 90% interval 1.16 to 1.41. Synonymous variants: 98 observed, 87.95 expected, observed/expected ratio (o/e) 1.11, 90% interval 0.94 to 1.32.
Homologues: Orthologues: chimpanzee TNFRSF17 (99% identical), macaque TNFRSF17 (91% identical), rabbit TNFRSF17 (75% identical), guinea pig TNFRSF17 (74% identical), dog TNFRSF17 (72% identical), pig TNFRSF17 (67% identical), mouse Tnfrsf17 (65% identical). Paralogues in human: TNFRSF13C (22% identical).
Diseases named in the same sentence as TNFRSF17 in open-access papers:
TNFRSF17 is named in the same sentence as 164 diseases in open-access papers, as found by Europe PMC text mining. Sharing a sentence is not in itself a finding about the gene and the disease. The quoted sentences say what the papers report.
multiple myeloma (759 papers, 2009 to 2026). "The first was TNFRSF17, which was known to encode the B-cell maturation antigen and was associated with the pathogenesis and treatment of multiple myeloma and colon cancer." (PMID 38384303, 2024). "Preclinical models found that the overexpression and activation of TNFRSF17 was associated with multiple myeloma, supporting its potential utility as a therapeutic target." (PMID 39007147, 2024). "Specifically, TNFSF13B expression had close interactions with macrophage marker genes, namely, TLR and S100A9 genes; their receptor genes, TNFRSF13B and TNFRSF17, showed significant associations with the myeloma-related genes CD38, SDC1, and MYEOV." (PMID 34150664, 2021). "B-cell maturation antigen, BCMA/TNFRSF17 is highly expressed on most of malignant plasma cells and represents a promising novel target for multiple myeloma therapy." (PMID 38284882, 2024). "Previous studies indicated that TNFRSF17 has a dispensable role in overall B cells homeostasis and is an important surface protein supporting the survival of multiple myeloma cells." (PMID 39007147, 2024). "Ligand activation of TNFRSF17 in multiple myeloma cells facilitates proliferation and drug resistance." (PMID 38649856, 2024). "While TNFRSF17 (BCMA) was highly specific for myeloma samples, other immunotherapy targets such as CD38, CD138 (SDC1) and SLAMF7 were not or only moderately higher expressed in MM versus healthy plasma cells." (PMID 38942927, 2024). "And significant clinical responses in patients with refractory multiple myeloma who failed at least three prior treatments had been achieved by the anti-TNFRSF17 antibody-drug conjugate." (PMID 39007147, 2024). "BCMA (TNFRSF17) is the target that has paved the way in myeloma, achieving an impressive 81% overall response rate (ORR) in a first-in-human trial." (PMID 39095991, 2024). "In multiple myeloma (MM) studies, IBI379 effectively linked T cells and plasma cells, inducing T cell activation, proliferation, and clearance of TNFRSF17+ plasma cells." (PMID 38440734, 2024). "As a B cell transcriptional coactivator, POU2AF1 regulates the expression of B cell maturation factor TNFRSF17 and stimulates the growth of myeloma cells." (PMID 35517856, 2022). "Both TNFRSF13B and TNFRSF17 surface expressions were upregulated on patient myeloma cells versus plasma cells from the healthy controls." (PMID 34150664, 2021). "CD19, SDC1 (CD138), CD38, SLAMF7, and TNFRSF17 (BCMA) were selected for targeting multiple myeloma (MM)." (PMID 34975912, 2021). "Our results demonstrated that S100A9 administration upregulated TNFRSF13B and TNFRSF17 surface expressions on myeloma cells, indicating crosstalk between TLR activation and TNFSF13B signaling." (PMID 34150664, 2021). "It is worth noting that B-cell maturation antigen (BCMA) is a transmembrane glycoprotein in TNFRSF17, and current targeted immunotherapy for BCMA has been used in clinical trials of multiple myeloma with satisfactory results." (PMID 33215029, 2020). "CD3 molecules deliver the first activation signal to T cells, and previous studies showed that IBI379 can effectively target TNFRSF17 and CD3, and inducing T cell activation, proliferation, and clearance of TNFRSF17+ plasma cells in multiple myeloma (MM) patients." (PMID 38440734, 2024). "TNFRSF17 is a biomarker of tumor load in multiple myeloma and a target of several immunotherapies." (PMID 37285836, 2023). "A clear separation of plasma/myeloma cells from BME immune cells was apparent from the enrichment of CD138+ cells and the high expression of the plasma cell marker TNFRSF17 encoding for BCMA." (PMID 34845188, 2021). "TNFRSF17, encoding for the B-Cell Maturation Antigen (BCMA), is currently being actively investigated as a potential therapeutic target in hematological malignancies such as multiple myeloma." (PMID 34680435, 2021). "TNFRSF17-targeting CAR T cells could effectively kill multiple myeloma cells." (PMID 38649856, 2024).
multiple myeloma (continued). "Transcriptomic analysis revealed deletion of 16p in the majority of the multiple myeloma cells; it is worth noting that the BCMA gene (TNFRSF17) is located on 16p13.13." (PMID 39175472, 2024). "The first CAR T cells targeting BCMA, also known as TNFRSF17 or CD296, were pre-clinically tested in 2013 on myeloma cell lines and showed a marked activity against them." (PMID 35886976, 2022). "B cell maturation antigen (BCMA), a transmembrane glycoprotein member of the tumor necrosis factor receptor superfamily 17 (TNFRSF17), highly expressed on the plasma cells of Multiple myeloma (MM) patients, as well as the normal population." (PMID 35144648, 2022). "Compared to the MGUS, MM patients were characterized by an evident rise in MYEOV+ myeloma cells, in which a clear upregulation of TNFSF13B receptors, TNFRSF13B and TNFRSF17, was detected." (PMID 34150664, 2021). "BCMA (B-cell maturation antigen; CD269; TNFRSF17) is selectively over-expressed during the malignant transformation of plasma cells, making it an ideal target for the treatment of multiple myeloma." (PMID 38783333, 2024). "BCMA, a member of the tumor necrosis factor receptor superfamily 17 (TNFRSF17) and a transmembrane glycoprotein, stands as the key surface antigen target for CAR-T cell therapy for the treatment of multiple myeloma." (PMID 38732213, 2024). "For multiple myeloma (MM), the majority of currently available CAR T-cell products target the B-cell maturation antigen (BCMA), also termed TNFRSF17, which is selectively expressed on mature B lymphocytes and has a relevant role for their survival and proliferation." (PMID 37061680, 2023). "Since 2017, the FDA has approved six CAR T-cell therapies for the treatment of CD19 or B-cell maturation antigen (BCMA, also referred as TNFRSF17, CD269) expressing hematological malignancies including ALL, non-Hodgkin lymphoma (NHL), and multiple myeloma (MM)." (PMID 36497465, 2022). "BCMA, a membrane protein also known as tumor necrosis factor receptor superfamily 17 (TNFRSF17), has been reported to be highly expressed by mature B-cells, including MM cells, and can promote myeloma cell growth in humans." (PMID 32659909, 2020). "Interestingly, the other blood tumor clinical CAR-T target genes, CD22 (in Phase 1 trials) and TNFRSF17 (encoding the BCMA protein and FDA-approved against multiple myeloma), are not essential in any cell line of their respective indications analyzed here." (PMID 37835579, 2023). "BCMA, CD269, or the tumor necrosis factor receptor superfamily member 17 (TNFRSF17) is a kind of transmembrane glycoprotein that plays an important role in the differentiation of B cells and the proliferation of malignant myeloma cells by combining with BAFF and APRIL." (PMID 34867949, 2021). "The most widely studied myeloma CAR target is none other than the B-cell maturation antigen (BCMA), a tumor necrosis factor receptor superfamily member 17 (TNFRSF17)." (PMID 33927192, 2021). "BCMA is known as CD269 and TNF receptor superfamily 17 (TNFRSF17) 58, and expressed in plasma cells and myeloma cells rather than in normal tissues and hematopoietic stem cells." (PMID 33746596, 2021).
leukemia (31 papers, 2011 to 2025). A malignant (clonal) hematologic disorder, involving hematopoietic stem cells and characterized by the presence of primitive or atypical myeloid or lymphoid cells in the bone marrow and the blood. "It was reported that TNFSF13 could support leukemia cell proliferation in an NF-κB-dependent manner by binding TNFRSF17 and suppressed apoptosis." (PMID 33215029, 2020).
lupus (26 papers, 2014 to 2026). "To evaluate further the role of BCMA on the expression of BAFF in autoimmunity, we studied the BAFF-producing innate immune cells in spleens of female naïve C57BL/6 (WT) mice and congenic lupus-prone B6.Faslpr/J mice, and compared mice sufficient or deficient in the gene Tnfrsf17 that encodes BCMA." (PMID 25010693, 2014). "Therefore, we speculate that TNFRSF17 plays a pathogenic role in both PBMCs and local kidney tissue of LN patients, and further investigation into the possibility of targeting TNFRSF17 for the treatment of lupus is warranted." (PMID 38440734, 2024). "It is worth noting that TNFRSF17 can serve as a biomarker in patients with systemic lupus erythematosus." (PMID 34737763, 2021).
breast carcinoma (14 papers, 2008 to 2025). "The expression of TNFRSF17 is associated with the development of breast cancer, ovarian cancer, and colon cancer." (PMID 36241983, 2022). "In breast cancer several TNF receptor superfamily (TNFRSF) members BAFF, APRIL, BCMA (TNFRSF17) and TACI (TNFRSF13B) have been associated with tumor initiation and progression." (PMID 33816291, 2021). "In addition, TNFRSF17, also known as B cell maturation antigen, can induce breast cancer cell stemness mediated by B cell activating factor and a proliferation-inducing ligand." (PMID 34737763, 2021). "TNFRSF17 and TNFRSF13B, members of the tumor necrosis factor receptor superfamily, are primarily involved in the maturation of B lymphocytes and are associated with tumor growth and invasiveness and may serve as therapeutic targets in breast cancer." (PMID 35087563, 2021). "First, by analyzing a large breast cancer study (MetaBRIC study), we found that APRIL (TNFSF13), BAFF (TNFSF13B), and BCMA (TNFRSF17) were expressed in 76% of the studied cohort." (PMID 30131941, 2018).
glioblastoma (12 papers, 2013 to 2023). The most malignant astrocytic tumor (WHO grade IV). "On average, TNFRSF17 mutations are found in 0.50% of all cancers; the most common types are colorectal, colon cancer, glioblastoma, lung cancer, and malignant cancer melanomas." (PMID 36251702, 2022).
plasmacytoma (10 papers, 2015 to 2025). Plasmacytoma is a localized mass of neoplastic monoclonal plasma cells that represents approximately 5% of all plasma cell neoplasms. "At relapse, computed tomography (CT)-guided biopsy of an isolated left sacral ala plasmacytoma confirmed loss of TNFRSF17 by single-cell RNA-sequencing (scRNA-seq) and flow cytometry." (PMID 37653344, 2023).
ovarian carcinoma (9 papers, 2018 to 2022). A malignant neoplasm originating from the surface ovarian epithelium. "TNFRSF17 expression was restricted to plasma cell high tumours regardless of the presence of other tumour-infiltrating lymphocytes (T cells, memory B cells) and linked to an improved survival in ovarian cancer." (PMID 34238352, 2021). "Previous literature had reported the prognostic role of TNFRSF17 in various cancers, including colon cancer, gastric cancer, lung cancer and ovarian cancer." (PMID 36203424, 2022).
colon cancer (8 papers, 2019 to 2024). "Researches from Chae SC suggested that TNFRSF17 may be a candidate gene associated with the pathogenesis of colon cancer and haplotype of TNFRSF17 polymorphism appears to be a marker of susceptibility to colon cancer." (PMID 33287740, 2020). "This study determined that IRF4 and TNFRSF17 were immune-related genes in colon cancer, providing immune-related prognostic biomarkers for colon cancer." (PMID 34900677, 2021). "The MOD of MS4A1 and TNFRSF17 showed that the expression of MS4A1 and TNFRSF17 in the cell membrane of colon cancer was significantly lower than that of adjacent tissues (P<0.001)." (PMID 36203424, 2022).
lung carcinoma (6 papers, 2017 to 2023). "The results of immunohistochemical analysis showed that compared with the stage I lung cancer group, the expression levels of COPG2IT1 and HLA.DQA1 in the stage III lung cancer group were significantly increased, and the expression levels of LYN, C3 and TNFRSF17 were significantly decreased." (PMID 33215029, 2020). "Furthermore, plasma B cells express marker genes CD38, TNFRSF17(BCMA), and IGHG1/IGHG4, which inhibit cell growth in the early stage of NSCLC but play the opposite role of promoting cell growth in advanced tumors, thus exhibiting heterogeneity in lung cancer progression." (PMID 37187731, 2023).
Autoimmunity (5 papers, 2014 to 2026). The occurrence of an immune reaction against the organism's own cells or tissues. "The proliferation-inducing ligand TNFSF13 (tumor necrosis factor superfamily member 13), which is the ligand for TNFRSF17/BCMA, was identified as an essential gene for B-cell development, autoimmunity, and cancer." (PMID 36059650, 2022).
COVID-19 (5 papers, 2021 to 2024). A disease caused by infection with severe acute respiratory syndrome coronavirus 2. "Patients with mild COVID-19 displayed a marked interaction between neutrophil and plasmablasts through BAFF (TNFSF13B) and BAFF receptors (encoded by TNFRSF13C, TNFRSF13B, or TNFRSF17)." (PMID 34548411, 2021). "B cell maturation antigen TNFRSF17 (BCMA) had increased expression in the np-PB groups, (COVID-19 in adults and dengue in children) and may reflect the increased maturity of the np-PB groups." (PMID 37638019, 2023).
influenza (4 papers, 2017 to 2025). An acute viral infection of the respiratory tract, occurring in isolated cases, in epidemics, or in pandemics; it is caused by serologically different strains of viruses (influenzaviruses) designated A, B, and C, has a 3-day incubation period, and usually lasts for 3 to 10 days. "This study marks the first instance of detecting both JCHAIN and TNFRSF17 on Days 0 and 7 following vaccination, elucidating their participation in influenza vaccine-related pathways." (PMID 40332395, 2025).
pancreatic cancer (4 papers, 2020 to 2022). "Our analyses revealed that the immune-related genes CCR4, CD19, TNFSF8, SH2D1A, ICOS, IGKV1D-39, and TNFRSF17 may be implicated in the immunophenotyping of pancreatic cancer." (PMID 34737763, 2021). "The results revealed seven immune-related genes (CCR4, CD19, TNFSF8, SH2D1A, ICOS, IGKV1D-39, and TNFRSF17) could potentially influence the immunophenotyping of pancreatic cancer." (PMID 34737763, 2021).
lymphopenia (3 papers, 2021 to 2025). Reduction in the number of lymphocytes. "The decrease in circulating soluble TNFRSF17 could be interpreted as a consequence of transient lymphopenia prior to seroconversion (see later)." (PMID 33724185, 2021).
lung adenocarcinoma (2 papers, 2017 to 2024). A carcinoma that arises from the lung and is characterized by the presence of malignant glandular epithelial cells. "Bioinformatic analysis showed that the levels of ERβ and TNFRSF17 were elevated in lung adenocarcinoma, and were closely related to tumor stages and nodal metastasis status." (PMID 38649856, 2024). "Our results also verified that TNFRSF17 expression was higher in lung adenocarcinoma than that in normal tissues, and was significantly correlated to LAC stage and nodal metastasis status." (PMID 38649856, 2024). "However, the role of TNFRSF17 in lung adenocarcinoma remains largely unknown." (PMID 38649856, 2024).
schizophrenia (2 papers, 2016 to 2025). A major psychotic disorder characterized by abnormalities in the perception or expression of reality. "Furthermore, TNFRSF17 (Tier B evidence for schizophrenia) SERPING1 (Tier B evidence for schizophrenia) have approved drugs." (PMID 40281223, 2025). "Among them, AGER (schizophrenia), CD40 (schizophrenia & bipolar), TNFRSF17 (schizophrenia), ACE (schizophrenia & Alzheimer’s) and SEPRING1 (schizophrenia) have drugs approved or in advanced clinical trials for several indications including cardiovascular and autoimmune conditions." (PMID 40281223, 2025).
yellow fever (2 papers, 2017 to 2024). "A member of the B cell signaling pathway triggered upon B cell activation (TNFRSF17, a receptor for BLyS-BAFF) was identified as a key predictive factor for neutralizing antibody response to yellow fever vaccination." (PMID 38633249, 2024).
allergic asthma (1 paper, 2022). A asthma with a basis in a pathological type I hypersensitivity reaction. "Similar to knockout mice with allergic asthma, it is possible that animals affected with FEK have an abnormal NF-kappa-B activation due to defective expression of TNFRSF17 and TNFRSF21 genes, as suggested by the current GWAS study." (PMID 35782544, 2022).
asthma (1 paper, 2024). "In OVA-sensitised and challenged mice, BAFF (which biological function is mediated by TNFRSF17) expression is increased together with increased IgE production and bronchial thickening suggesting the key role in asthma pathogenesis." (PMID 39085570, 2024).
cholera (1 paper, 2021). "By transcriptionally profiling PBMCs from Swedish volunteers receiving the oral cholera Dukoral® vaccine, we identify TNF Receptor Superfamily member 17 (TNFRSF17), a gene encoding the protein B cell maturation antigen (BCMA) as a candidate biomarker." (PMID 33828557, 2021).
coronary artery disease (1 paper, 2024). "The two-sample MR analysis used in this work, which is based on a large GWAS dataset of TNFRSF17 (exposure) and myocardial infarction (outcome), is the first investigation of the causal relationship between TNFRSF17 levels and coronary artery disease." (PMID 38977728, 2024).
depression (1 paper, 2021). "These included several interesting candidates including TNFRSF17, previously reported to be significantly upregulated in women with PPD and MMP8, a matrix metalloproteinase gene, associated with depression in a genome-wide association study." (PMID 33664235, 2021).